LGALS3 (galectin 3)
Diseases named in the same sentence as LGALS3 in open-access papers (continued):
Sharing a sentence is not in itself a finding about the gene and the disease.
cancer (continued). "A higher level of Galectin 3 in CAKs, in comparison to control keratinocytes, which we have also demonstrated, has not been previously shown and might contribute to increased cancer cell movement through activation of the PKC/ERK pathway." (PMID 36123693, 2022). "The shorter and nonbranched MCP could recognize and bind tightly with galectin-3, whose overexpression was related to a variety of malignant tumors." (PMID 36432183, 2022). "Galectin-3 from peripheral blood could be affected by other pathologies, such as cancer or non-cardiac fibrotic diseases." (PMID 35039576, 2022). "Additional evidence suggests that galectin-3 could also act as a negative immune checkpoint in other types of cancers." (PMID 34572756, 2021). "Galectin-3 protein expression in the cytoplasm and nucleus was mainly seen in the malignant FPTLs (FVPTC).It was focally seen in 3/51 cases of benign lesions (7.9% of HNs and 0.0 % of FA), in 3/12 (25 %) NIFTP, and in 15/20 carcinomas (52.9% FVPTC and 0.0% of FC)." (PMID 34711014, 2021). "Moreover, despite the absence of a canonical RNA-binding domain, Galectin-3 is a non-classic RNA-binding protein (RBP) able to stabilise mucin MUC4 mRNAs in cancer cells." (PMID 32398681, 2020). "As a matrix protein, M2BP, which seems to be mediated by β1 integrins and is independent of galectin-3, may play a strong role in apoptosis of cancer cells by means of cellular interactions." (PMID 29849819, 2018). "MUC1 and galectin-3 are both commonly over-expressed by solid tumours and their interactive effects on EGFR activation may have an important influence on EGFR-mediated tumourigenesis and cancer progression, and on the effectiveness of EGFR-targeted therapy." (PMID 28731466, 2017). "Interestingly, it has been reported that inhibitors of galectin-3 function (β-lactose, a dominant-negative form of galectin-3, Gal-3C and anti-galectin-3 antibody M3/38) or revacept prevented platelet-dependent COX-2 overexpression in cancer cells." (PMID 26551717, 2015). "Additionally, these results were not statistically significant with P value >0.05 for the galectin-3 + HBME-1 in differentiating all benign lesions from malignant tumors." (PMID 19826479, 2009). "Sometimes, galectin-3 combined with another biomarker was often utilized simultaneously in prognostic outcome analyses, showing it might not be an independent factor affecting the prognosis of cancer patients." (PMID 30410421, 2018). "Galectin-3 has been shown to co-express with MUC1 and promote the adhesion of the cancer cells to endothelium by exposing the small CAMs that are normally shielded." (PMID 37444377, 2023). "Based on evidence for its roles in metastatic potential in cancer cells, the availability of specific inhibitors and no previous reports in NPC, galectin-3 was selected for further validations." (PMID 33020562, 2020). "Interestingly, galectin-3-mediated cell proliferation, migration and invasion was reduced by treatment with DKK1, which suggested that the upregulation of WNT-1 expression by galectin-3 may play an important role in Wnt/β-catenin pathway activation in galectin-3-positive cancer cells." (PMID 32183420, 2020). "We found that these markers combinations of galectin-3+HBME-1; galectin-3+CK19 or HBME-1+ CK19 do not improve the sensitivity or specificity for the distinction between benign and malignant thyroid lesions." (PMID 20181018, 2010). "The cleavage of nidogen-1 by PSA may lead to disruption of basement membrane structure and may facilitate cancer cell invasion, but our results suggest that PSA-generated nidogen-1 or galectin-3 fragments do not mediate the antiangiogenic function of PSA." (PMID 25237904, 2014). "Furthermore, using a combination panel of three markers (galectin-3+ HBME-1+ CK19) also did not increase the sensitivity or specificity for the distinction between benign and malignant thyroid lesions." (PMID 20181018, 2010).
cancer (continued). "The use of two or three markers might be more relevant than just one as recently shown on a series of 37 fine-needle aspiration biopsies using a panel of markers consisting of galectin-3, HBME1 and RET, where none of the 20 malignant tumours was negative for this panel." (PMID 16251880, 2005).
infection (179 papers, 2009 to 2025). The state of being infected such as from the introduction of a foreign agent such as serum, vaccine, antigenic substance or organism. "This antagonism is evident in infections with Listeria monocytogenes and Group A Streptococcus, where galectin-3 suppresses autophagy-associated ubiquitination, thereby limiting bacterial clearance." (PMID 40806347, 2025). "In the murine nasal infection model, galectin-3 accelerated the clearance of S. suis and alleviated pathological damage caused by the infection." (PMID 40696454, 2025). "Galectin-3 has also been linked to macrophage polarization during dengue virus infection, which is associated with infection severity." (PMID 37298569, 2023). "Many studies demonstrated that galectin-3 appears to mediate neutrophil migration and recruitment in bacteria-caused infection animal models." (PMID 35437453, 2022). "In contrast, higher numbers of neutrophils were found in the blood of galectin-3 deficient mice, suggesting the possibility that they were unable to reach the airways during infection." (PMID 32750085, 2020). "Galectin-3 deficient mice are more resistant to infection with the intracellular pathogen Histoplasma caspulatum, which has been linked to increased production of interleukin (IL)-17-associated cytokines by dendritic cells in these mice." (PMID 32750085, 2020). "Conversely, galectin-3 deficient mice exhibit increased susceptibility to infection with the pathogenic basidiomycetous yeast Cryptococcus neoformans." (PMID 32750085, 2020). "Galectin-3 deficient mice exhibited fewer neutrophils in their airways during infection, despite normal numbers of total lung neutrophils." (PMID 32750085, 2020). "In the 4D study, the level of galectin-3 was found to predict all-cause mortality, cardiovascular events, stroke, and mortality due to an infection." (PMID 27089335, 2016). "Galectin-3 has also been implicated in the pathogenesis of ventricular remodeling, infections, and various autoimmune and inflammatory processes." (PMID 27089335, 2016). "Galectin-3 has also been implicated in enhancing infection of human host cells by the parasite Trypanosoma cruzi." (PMID 24995007, 2014). "The results of current study showed that galectin-3 can be released extracellularly in lungs under pathogenic conditions such as an infection." (PMID 23527230, 2013). "In comparison, only 8 of 17 galectin-3-KO mice (47%) developed symptoms of ECM by day 8 post-infection, indicating that loss of galectin-3 conferred significant (p<0.0073, Fisher's exact test) protection from ECM." (PMID 19710907, 2009). "We next measured the susceptibility of galectin-3-KO mice to ECM following infection with Pb-A parasites." (PMID 19710907, 2009). "To test if the impaired neutrophil recruitment to the airways seen in galectin-3 mice was a consequence of reduced production of chemotactic factors, we determined the levels of cytokines in BAL fluid in wild-type and galectin-3 deficient mice at 36 hours post infection." (PMID 32750085, 2020). "Galectin-3-deficient mice had impaired neutrophil recruitment to the site of infection." (PMID 32750085, 2020). "Galectin-3 also has anti-fungal properties in infections caused by Candida species." (PMID 32455781, 2020). "In addition, LGALS3 gene (encoding galectin-3) was downregulated in trophoblasts from CZS-affected twins after ZIKVBR infection." (PMID 32745093, 2020). "Because galectin-3 deficiency was associated with higher vulnerability of mice to the infection, we hypothesize that galectin-3 contributes to the host resistance against the fungus." (PMID 19229338, 2009). "Thus, by exploring the development of cardiac alterations in the murine infection and its association with galectin-3 expression using different human isolates of T. cruzi fitting with DTUs I, V, and VI, only animals infected with the former strains developed moderate to severe myocarditis." (PMID 35046919, 2021).
infection (continued). "In a mouse model of intranasal infection with S. suis, intranasal administration of galectin-3 decreased bacterial load in multiple organs and alleviated the pathological damage resulting from the infection." (PMID 40696454, 2025). "The ability of Galectin-3 to promote migration of immune cells to infection sites can exacerbate inflammation and tissue damage." (PMID 41036542, 2025). "For example, in infection by Candida albicans, it was observed that galectin-3 negatively affects neutrophil functions, and reduced galectin-3 expression increases human neutrophil reactive oxygen species (ROS) production." (PMID 40649198, 2025). "This infection also induces other immune responses that indirectly upregulate GBPs expression, such as Unfolded Protein Response and Galectin-3 immune activation." (PMID 38404575, 2024). "Among those GO terms, at the acute infection stage, some targeted DEmRNAs (e.g., Ccl2, Lgals3, H2-DMb2, Ripk2, and Ndfip1) were enriched in the “regulation of T cell activation” term (GO:0050863)." (PMID 38229193, 2024). "With similar expression levels of SLO, Cap(+) and Cap(–) strains showed a similar percentage of galectin-3, a marker for phagosome rupture, during 1–2 h of infection, which was further decreased in both Pnga1 stains." (PMID 38819157, 2024). "The mean levels of galectin-3 in CV death, infection-related death, and malignancy-related death were 45.1 ± 19.0, 40.8 ± 15.6, and 53.2 ± 19.9 ng/mL, respectively (p = 0.755)." (PMID 38195853, 2024). "In gastric epithelial cells infected with Helicobacter pylori, the secretion of Galectin-3 by the cells can bind to the bacteria’s LPS, prompting phagocytes to aggregate rapidly at the site of infection." (PMID 37511297, 2023). "Prominent examples for galectin-3-mediated and infection-related activities include its ability to facilitate herpes simplex virus cell entry and to induce the death of human immunodeficiency virus (HIV)-infected macrophages." (PMID 37238973, 2023). "Galectin-3 (Gal-3), multifunctional protein plays important roles in inflammatory response, infection and fibrosis." (PMID 36702907, 2023). "The concentration of secreted galectin-3 decreased 40% at 1 min post-infection but gradually increased up to 20% over the origin level at the subsequent time points." (PMID 36595499, 2023). "In this study, we identified and characterized large yellow croaker Galectin-3 (LcGal-3), including its structural features, phylogenetic relationship, and expression profile in different tissues after infection with P. plecoglossicida." (PMID 37511297, 2023). "Galectin-3 has been shown to inhibit the differentiation of B cells into plasma cells, and galectin-3 knockout mice show increased numbers of plasma cells and develop hypergammaglobulinemia upon infection." (PMID 38332916, 2023). "A549 cells were transfected with the galectin-3 expression vector pCR3.1-Gal-3-Flag, followed by infection with IAV." (PMID 36823664, 2023). "Galectin-3 is a protein that has been implicated in various aspects of HIV infection, including viral entry, infection, dissemination, and pathogenesis." (PMID 37298569, 2023). "By contrast, only ~0.4 ng ml-1 of galectin-3 was detected in the conditioned medium of hVECs before infection." (PMID 36595499, 2023). "Our biomarker signature showed galectin-3 was present in all cohorts, while lower in healthy controls, indicating a role in infection." (PMID 37064248, 2023). "To study the role of galectin-3 in host defense against influenza virus infection, we compared the survival curves and body weight changes between Gal-3−/− and WT mice after intranasal infection with IAV." (PMID 36823664, 2023). "Overall, Galectin-3’s complex and context-dependent role in immune signaling pathways highlights the need for understanding its precise functions in various infections to identify its potential as a therapeutic target or biomarker for disease severity." (PMID 37298569, 2023).
infection (continued). "Two-photon microscopy was used to observe the number and morphology of fungal mycelia in corneas of wild type FK mice and galectin-3−/− FK mice on day 5 after infection." (PMID 35437453, 2022). "Galectin-3 responds directly and indirectly to infection (e.g., binds pathogens and activates the innate immune system), and reduces inflammation arising from NF-κB and the NLRP3 inflammasome." (PMID 36615679, 2022). "Confocal microscopy demonstrated a higher proportion of MDM phagosomes containing bacteria were associated with galectin 3, a marker for vacuole integrity, after infection with TIGR4 compared to infection with TIGR4Δply." (PMID 35835695, 2022). "Several studies report that galectin-3 is a component of the innate immune system, participating in the organism’s defense mechanisms against infection, promoting macrophage and neutrophil survival, and promoting phagocytosis." (PMID 36292107, 2022). "A previous study revealed that the expression of Galectin-3 was upregulated in response to HIV-1 CRF07_BC infection, and the endogenous Galectin-3 facilitated the binding of Alix-Gag p6 complex to promote HIV-1 budding." (PMID 35450078, 2022). "Galectin-3 involves in the migration of neutrophils to sites of infection or inflammation, activates neutrophils and promotes their adhesion." (PMID 35083706, 2022). "Galectin-3 is reported to be effective in controlling infection extension in bacterial lung infection and renal fungi infection." (PMID 35437453, 2022). "Curiously, by 4h post infection, galectin-3, -8, and -9 formed puncta in the cytosol of R. equi infected cells, although the nature of these puncta is unclear." (PMID 34473814, 2021). "This is consistent with Mtb recruitment of these galectins, which occurs as early as 3h post-infection, while Salmonella enterica serovar Typhimurium recruits galectin-3, -8, and -9 to broken vacuoles as early as 1h post-infection." (PMID 34473814, 2021). "Galectin-3 recruitment peaked at 4h post-infection, with recruitment to ~12% of R. equi at 4h and declining to ~5% by 16h." (PMID 34473814, 2021). "Studies in WT and galectin-3 knockout Swiss mice during the acute infection with T. cruzi Y strain contributed to unveiling the effect of galectin-3 in the modulation of serum cytokines." (PMID 35046919, 2021). "In fact, galectin-3 was found to be upregulated in macrophages of the inflammatory infiltrate in hearts from C57Bl/6 mice for a total of 8 months post-infection." (PMID 35046919, 2021). "Intracellular galectin-3 signal changed minimally in response to infection, with a significant reduction of galectin-3 mean fluorescent intensity (MFI) noted only in alveolar macrophages." (PMID 32750085, 2020). "Next, we examined the potential mechanism for how galectin-3 positively mediates HIV-1 CRF07_BC infection." (PMID 32485969, 2020). "Galectin-3 has been established as a marker for vacuole integrity during infection with S. enterica serovar Typhimurium, Shigella flexneri, and Trypanosoma cruzi." (PMID 32209695, 2020). "Our results suggested that HIV-1 CRF07_BC infection induced galectin-3 expression and amino acid deletion in the p6Gag-reduced Alix–Gag interaction, subsequently ameliorating virus budding." (PMID 32326345, 2020). "Almost all immune cells were galectin-3-positive, both pre- and post-infection, with an increase in the % positive cells seen only in inflammatory monocytes (83% to 99% galectin-3 positive), and endothelial cells (26% to 59% galectin-3 positive)." (PMID 32750085, 2020). "This study aims to examine the viral characteristics of HIV-1 CRF07_BC virus and the role of extracellular galectin-3 in HIV-1 CRF07_BC infection." (PMID 32485969, 2020). "We also provide evidence that extracellular galectin-3 enhanced CRF07_BC infection using a recombinant human galectin-3 co-treatment strategy." (PMID 32485969, 2020).
infection (continued). "Our data demonstrate that galectin-3 acts as a soluble host protein that can stabilize virus-cell interactions leading to promotion of HIV-1 CRF07_BC infection." (PMID 32485969, 2020). "In this study, we evaluated the characterization of HIV-1 CRF07_BC from our cohort in Taiwan, as well as the potential role that galectin-3 plays in HIV-1 CRF07_BC infection." (PMID 32326345, 2020). "Through our immunophenotyping and neutrophil adoptive transfer studies we found that extrinsic galectin-3 is required for effective neutrophil egress from the blood vessels and into the site of the infection within the airways." (PMID 32750085, 2020). "Results indicate that significant higher serum galectin-3 was measured in CRF07_BC infected patients and CRF07_BC infection triggered significant galectin-3 expression (p < 0.01)." (PMID 32485969, 2020). "To validate the key role Galectin-3 plays in activating phagocytosis, we presently KD Galectin-3 protein levels in cultured primary microglia through lentiviral infection with Gal-3-shRNA, generating Gal-3-KD microglia." (PMID 30930748, 2019). "Four weeks after infection level of anti-PDC-E2 IgA in the serum of WT mice was significantly higher compared to the group of Lgals3−/− mice." (PMID 31231399, 2019). "Negligible deposit of collagen was observed in Lgals3−/− and Gal-3 inhibitor treated mice 3 months after infection." (PMID 31231399, 2019). "Four weeks after infection only mild infiltration was noticed in the livers of Lgals3−/− mice, while intensive parenchymal and bile duct infiltrations and bile duct obliterations were observed in the livers of infected WT mice." (PMID 31231399, 2019). "Galectin-3 positive cell infiltration was visible as early as 48 hours after EMCV inoculation, with expression of galectin-3 increasing further by 96 hours after the infection, most markedly in degenerated fibrotic lesions of cardiac tissues." (PMID 30673749, 2019). "Serum levels of AST and ALT after infection with N. aromaticivorans were significantly lower in the group of Lgals3−/− mice in comparison with the group of WT mice." (PMID 31231399, 2019). "Three days after infection percentage of dendritic cells in the spleen and liver of Lgals3−/− mice was significantly lower in comparison with WT infected mice." (PMID 31231399, 2019). "Four weeks after infection significantly lower percentage of CD11c+, CD11c+CD11b+, and CD11c+CD1d+ dendritic cells was detected in the livers of Lgals3−/− mice compared with WT mice." (PMID 31231399, 2019). "At chronicity, LIC infection induced similar slight macrophage infiltration in both wild type and Lgals3−/− mice." (PMID 30425972, 2018). "We transferred 50 × 103 ORF8 TCR TN CD8+ T cells into WT and galectin-3 KO mice 1 day before MHV68 infection and measured the frequencies of expanded cells 7 days later." (PMID 30388704, 2018). "We, therefore, investigated the role of galectin-3 in the activation of CD8+ T cells during MHV68 infection, as its contribution in anti-viral CD8+ T cell immunity remains ill defined." (PMID 30388704, 2018). "Sorted H-2Kb-SIINFEKL-specific CD8+ T cells during the acute as well as memory stage of infection were analyzed for recruitment of galectin-3 at the immune synapse." (PMID 30388704, 2018). "Given its critical role during activation of T cells, we chose galectin-3 for elucidating its role in CD8 T cell response induction during γ-HV infection." (PMID 30388704, 2018). "Galectin-3 has been associated with a plethora of proinflammatory functions because of its ability, among others, to promote neutrophil activation and because of the reduction in neutrophil recruitment in models of infection in Gal-3-null mice." (PMID 27733579, 2017). "Galectin-3 production has also been reported in infection of the airways, and in some cases, participation of Gal-3 can be detrimental to the host." (PMID 28607536, 2017).